GSDMC (gasdermin C)
Diseases named in the same sentence as GSDMC in open-access papers (continued):
Sharing a sentence is not in itself a finding about the gene and the disease.
cancer (continued). "For example, under hypoxia, increased p-STAT3 levels promote the nuclear translocation of PD-L1 in cancer cells, leading to the upregulation of GSDMC transcription." (PMID 35990696, 2022). "Collectively, this study links metabolites with the pyroptosis pathway and illustrates how α-KG triggers DR6 endocytosis to bring about caspase-8/GSDMC-mediated pyroptosis, and thus, has application in cancer therapy." (PMID 35673561, 2022). "High expressions of GSDMA, GSDMB and GSDMC were associated with subtype C1 (Wound healing), C2 (INF-r dominant) and C6, indicating a cancer promoter role of these three members." (PMID 35164740, 2022). "In this research, we assessed the mRNA expression levels of GSDMC in pan-tumors and matching non-cancer normal tissues utilizing TGGA and TIMER databases." (PMID 36042287, 2022). "In brief, this study found a novel function of PD-L1 and identified that caspase-8/GSDMC mediates the pyroptosis pathway in cancer cells, which facilitates tumor necrosis." (PMID 35673561, 2022). "IHC staining analysis exhibited that GSDMC was mainly localized in the cytoplasm of cancer cells, and brown staining indicated positive staining." (PMID 36042287, 2022). "On the other hand, TNF-α derived from macrophages stimulates caspase-8 expression in cancer cells, which further specifically lyses GSDMC into N-GSDMC to induce pyroptosis." (PMID 35990696, 2022). "Meanwhile, it has been reported that other members of the gasdermin family, like GSDMB, GSDMC also involved in the pyroptosis of cancer cells." (PMID 35756622, 2022). "The available evidence indicates that PD-1/L1 can control GSDMC-mediated pyroptosis in cancer cells." (PMID 35368686, 2022). "Our pan-cancer analysis indicates that the expression of GSDM genes (in particular GSDMB, GSDMC, and GSDMD) was significantly associated with the survival of patients with certain types of urinary tract system cancer." (PMID 36003332, 2022). "Under hypoxic conditions the immune checkpoint inhibitor PD-L1 (programmed death ligand 1) was reported to interact with phosphorylated STAT3 in cancer cells to induce the transcription of GSDMC." (PMID 35608339, 2022). "The flanking region of hs1709 includes the protein-coding gene GSDMC that has an upregulated expression in some cancers." (PMID 34464437, 2021). "Of note, in a recent study, GSDMC-dependent pyroptosis occurred in cancer cells after treatment with anthracyclines, such as doxorubicin and epirubicin that are well-known ICD inducers, but not with most other chemotherapy drugs tested." (PMID 33406603, 2021). "Among the 12 cancers with significantly different expressions in normal tissues and cancer tissues, they were divided into low expression and high expression groups according to the median value of GSDMC expression." (PMID 34778452, 2021). "Caspase-8 activated by TNF-α cleaves GSDMC at it linker, liberating the GSDMC N-terminal domain to trigger pyroptosis in cancer cells." (PMID 33941231, 2021). "Compared with the normal epithelial cell line HK2, the expression of GSDMC was increased in cancer cell lines Caki-1, ACHN, Caki-2, and A498 cell lines." (PMID 34778452, 2021). "GSDMC is cleaved by caspase-8 with TNFα treatment, and also can be cleaved by caspase-6 in response to reactive oxygen species (ROS) insult in cancer cells." (PMID 34421915, 2021). "Immunohistological analysis confirmed that GSDMC was not expressed in normal colonic tissues, whereas GSDMC was expressed in the cancer tissues of almost all CRCs." (PMID 27835699, 2016). "PD-1-mediated GSDMC expression converts apoptosis to necroptosis in cancer cells." (PMID 41584044, 2026). "Interestingly, none of the other gasdermin family members displayed a significant correlation with OS or RFS for PDAC, whereas GSDMC expression was also correlated with outcome for several other cancers." (PMID 39297408, 2024). "Silencing GSDMC altered cell morphology, reduced invasion, and decreased cancer stem cell numbers." (PMID 39297408, 2024).
cancer (continued). "In most cancers, the methylation of the GSDMC promoter is lower in tumors than in normal tissues." (PMID 39062587, 2024). "The intricate dynamics of GSDMC in cancer development warrant deeper exploration." (PMID 38304430, 2024). "Furthermore, it has been shown that PD-L1 and p-Stat3 induce GSDMC expression synergistically, and caspase-8 activated upon TNFα stimulation cleaves GSDMC at Asp365, inducing pyroptosis of cancer cells." (PMID 37771587, 2023). "While nearly all chemotherapy drugs can enhance GSDMC expression and promote nPD-L1 translocation, specific antibiotics, such as daunorubicin, doxorubicin, epirubicin, and actinomycin-D, have been shown to activate caspase-8 and then cleave GSDMC, initiating pyroptosis in cancer cells." (PMID 38066523, 2023). "This suggests a potential oncogenic role for GSDMC in cancer progression." (PMID 38066523, 2023). "The role of GSDMC in cancer development is a matter of debate." (PMID 37771587, 2023). "Thus, further experimental validation is needed to investigate the link between the expression of GSDMC and the prognosis of cancer patients in BC and other kinds of cancers, including PAAD, COAD, KICH, etc." (PMID 36042287, 2022). "It is also valuable to study whether GSDMC/caspase-8-mediated pyrolysis has a role in other types of cancer." (PMID 35957895, 2022). "However, much further research is needed to investigate the link between the expression of GSDMC and cancer patient prognosis in other kinds of cancers, including PAAD, COAD, KICH, etc." (PMID 36042287, 2022). "We found that the CNV in most PRGs is gained in cancer, such as GSDMC, AIM2, and GSDMD." (PMID 35008400, 2022). "Almost all cancer types showed substantial upregulation of GSDMC and GSDMD expression." (PMID 35922531, 2022). "The elevated expression level of GSDMC, which could be induced by the nuclear translocated PD-L1, is required for the switching TNFα-induced apoptosis to pyroptosis in cancer cells." (PMID 34421915, 2021). "In addition, the function of GSDMC-mediated pyroptosis in cancer is worthy of further investigation." (PMID 33634141, 2021). "We analyzed the expression of GSDMC in 33 types of cancers in TCGA database." (PMID 34778452, 2021). "Extensive studies are warranted to completely define the role of GSDMC in cancer." (PMID 33634141, 2021). "The results showed that the expression of GSDMC was upregulated in most cancers." (PMID 34778452, 2021). "GSDMC, another effector of pyroptosis, correlates with poor survival in cancer patients." (PMID 34421915, 2021). "High expression of GSDMC is in relation to undesirable survival of cancer patients." (PMID 34589498, 2021). "Compared with normal gastric and esophageal tissues, GSDMC is downregulated in GC and esophageal cancer cells and may function as a cancer suppressor gene." (PMID 31501419, 2019). "Thus, we speculate that TNF-α may also contribute to the PARPi killing effect in GSDMC-positive cancer cells." (PMID 37883181, 2024). "PD‐L1‐mediated expression of gasdermin C (GSDMC) could switch cancer apoptosis to pyroptosis." (PMID 36237132, 2023). "Finally, a combination of the expression and prognostic significance of GSDMC in several kinds of cancers, we found that elevated expression of GSDMC might play as an unfavorable prognostic biomarker in BRCA patients." (PMID 36042287, 2022). "Moreover, GSDMC functions as an oncogene in multiply cancers and may serve as a potential therapeutic target." (PMID 35535333, 2022). "In addition, despite the lack of relevant studies, the caspase-8-GSDMC pathway may also play a role in RT, as it has been shown that PD-L1 could mediate the conversion of cancer cell apoptosis to pyroptosis by GSDMC." (PMID 36457125, 2022). "The influence of GSDMC deregulation on carcinogenesis may differ depending on the cancer type." (PMID 33634141, 2021).
cancer (continued). "For example, GSDMA, GSDMC, and GSDMD are underexpressed in esophageal and gastric cancers, while GSDMB is overexpressed and acts as an oncogene in these cancers." (PMID 40691738, 2025). "Caspase-8, a key enzyme in the extrinsic apoptosis pathway, has recently been shown to cleave Gasdermin C (GSDMC) under specific inflammatory conditions (e.g., high TNF-α and IFN-γ levels), inducing pyroptosis in cancer cells." (PMID 40918101, 2025). "A growing number of studies have reported that GSDMC expression is increased in a variety of cancers, including CRC, LUAD, and KIRC, and knockdown of GSDMC can inhibit the biological behavior of KIRC and CRC." (PMID 36882663, 2023). "In the genes that code for GSDMC, GSDMD, GSDME, and PJVK, ovarian cancer has the highest rate of copy number variation events of any cancer type." (PMID 37752941, 2023). "Our analysis of TGGA data demonstrated that GSDM genes (GSDMB, GSDMC, and GSDMD in particular) were upregulated in different types of cancers compared with the corresponding normal specimens." (PMID 36003332, 2022). "The GSDM family includes six members, GSDMA, GSDMB, GSDMC, GSDMD, GSDME (DFNA5), and PJVK (Pejvakin, DFNB59), which can induce pyroptosis, thereby regulating the tumorigenesis of various cancers." (PMID 36505798, 2022). "Under hypoxia, programmed death-ligand 1 (PD-L1) raises GSDMC expression, and GSDMC is cleaved by caspase-8, thereby transforming TNF-α-mediated apoptosis into pyroptosis in cancer cells." (PMID 36522335, 2022). "GSDMC, NLRP7, CASP5, PYCARD, IL18, IL1B and GSDMA were significantly upregulated in 22, 18, 18, 18, 18, 16 and 17 types of cancers, respectively." (PMID 35246158, 2022). "In cancer, pyroptosis has been shown to be triggered by almost all signaling pathways in which GSDME, GSDMD, GSDMC, or GSDMB serve as the executors." (PMID 35673561, 2022). "GSDMC, GSDMD, GSDME, ZBP1, AIM2, DHX9 and NLRP3 demonstrated significant amplification across cancers." (PMID 36605187, 2022). "Thus, it is unclear whether GSDMC promotes or inhibits cancer development." (PMID 35784306, 2022). "The expression of selected 6 PRGs (GSDMC, GSDMD, GSDME, NLRP3, NLRC4, and IL1B) was assessed in 6 types of cancers and adjacent normal tissues." (PMID 36605187, 2022). "Six GSDM family genes (i.e., GSDMA, GSDMB, GSDMC, GSDMD, GSDME, and PJVK) have long been described in other fields; however, they have been rarely investigated in a pan-cancer setting." (PMID 36003332, 2022). "Yet, because the biological function of GSDMC is rarely studied, its role in cancer is still not fully understood." (PMID 39062587, 2024). "Gasdermin C serves as a general marker for PARP-inhibitor therapy in cancers regardless of BRCA status through pyroptosis-augmented antitumor immunity." (PMID 37883181, 2024). "And we found that GSDMC increased PARPi sensitivity in multiple cancer types through expansion of memory CD8+ T cells in lymphoid tissue and tumors, suggesting the favorable role of CCP in PARPi therapy for cancer." (PMID 37883181, 2024). "GSDMA, GSDMC, and PJVK were expressed at low levels in all cancers." (PMID 35922531, 2022). "In pan-cancer, GSDMD had the relatively highest expression level while GSDMC had the lowest." (PMID 35164740, 2022). "GSDMB, GSDMC, GSDMD, GZMB, and GSDME displayed extensive CNV amplification across cancer types." (PMID 35620284, 2022). "No substantial correlations were observed between GSDMC expression levels and patient prognosis in other types of cancers." (PMID 36042287, 2022). "Intriguingly, it is reported that nuclear PD-L1 translocation could promote the transcription of GSDMC and switches the apoptosis induced by TNF-α to pyroptosis in cancer, which further indicated the relationship between pyroptosis and immune checkpoint." (PMID 35047095, 2022).
cancer (continued). "Significantly upregulated PRGs included PYCARD in 12 cancers; GSDMB in 10 cancers; IL18 in 9 cancers; GSDMD, CASP8, GZMB, and GPX4 in 8 cancers; AIM2 and CASP6 in 7 cancers; GZMA in 6 cancers; GSDME, CASP4 and DHX9 in 5 cancers; GSDMA and GSDMC in 4 cancers." (PMID 36605187, 2022). "GSDMC and GSDMD were found to be significantly upregulated in almost all cancer types." (PMID 35922531, 2022). "In fact, GSDMC, GSDMA, GSDMD, and AIM2 were the most upregulated genes across cancers." (PMID 36605187, 2022). "It was found that there were 15 cancers with fewer than 5 cancer patients in the normal group or lack of GSDMC expression data." (PMID 34778452, 2021). "Overexpressions of GSDMC and GSDMD have been observed in various types of cancer." (PMID 34858408, 2021). "In that study, the expression of GSDMC, but not other GSDMs, was increased in cancer cells by nuclear translocation of programmed death ligand 1 (PD-L1), which was induced by hypoxia or chemotherapeutic drugs." (PMID 33406603, 2021). "We found that different cancer cell lines exhibited distinct responses, including sensitivity and insensitivity, to DM-αKG-induced pyroptosis, and that these responses seemed to be unrelated to the expression of MDH1, DR6, caspase-8, and GSDMC." (PMID 34012073, 2021). "Collectively, no clear picture has emerged so far of whether GSDMC might promote or suppress cancer development." (PMID 39489845, 2024). "Similarly strong GSDMC expression can be detected in cancer‐positive lymph nodes, but not in cancer‐negative lymph nodes." (PMID 39297408, 2024). "We observed that NLRP7 (n = 8), AIM2 (n = 10), CASP8 (n = 6), GSDMA (n = 5), GSDMB (n = 8), and GSDMC (n = 12) mainly showed hypomethylation in most cancers, and PLCG1 (n = 11), NLRP6 (n = 13), ELANE (n = 11), CASP6 (n = 5), NLRC4 (n = 12), and PYCARD (n = 8) showed hypermethylation in most cancers." (PMID 35246158, 2022). "The results showed that the expression level of GSDMC is positively correlated with MSI or TMB in seven cancers (BRCA, COAD, READ, GBM, THCA, THYM, and LUSC) but negatively correlated with MSI or TMB in seven other cancers (CHOL, ESCA, KIRC, KIRP, LGG, PRAD, and SKCM)." (PMID 32778143, 2020). "GSDMC is not detectable in normal epithelial cells but is present in malignant melanoma, which may be related to the invasion and metastasis of these cancer cells." (PMID 31501419, 2019). "Taken together, the combination of OS, RFS, DSS, DMFS, and PPS and concern of bias, our findings illustrated the expression levels and prognostic value of GSDMC in several kinds of cancers, GSDMC might perform as a negative prognostic biomarker in BRCA patients." (PMID 36042287, 2022).
infection (4 papers, 2022 to 2025). The state of being infected such as from the introduction of a foreign agent such as serum, vaccine, antigenic substance or organism. "We aimed to disentangle a potential involvement of GSDMC in modulating gut inflammation by analysing infection and inflammation kinetics of GSDMC-deficient mice infected for 96 h with S. TmSPI2." (PMID 41370284, 2025). "However, we could not observe any changes in inflammation kinetics and severity (i.e., regeneration capacity) between GSDMC-deficient and -proficient mice in S. TmSPI2 infections." (PMID 41370284, 2025). "In contrast to GSDMD, GSDMC-deficiency does not have an impact on S. Tm loads in streptomycin-pretreated mice (at 48h p.i.) and its role during S. Tm infection remains poorly defined." (PMID 41370284, 2025). "Consistent with the role of GSDMC in anti-helminth response, one study reported that the specific ablation of Gsdmc1-4 genes in intestinal epithelial cells resulted in increased worm burden after infection with Heligmosomoides polygyrus." (PMID 39489845, 2024). "Furthering our understanding of GSDMC’s role in gut inflammation, both infection or autoimmunity driven may provide novel approaches to gut pathology and insight enabling strategies to target GSDMC in disease." (PMID 37266429, 2023). "However, it is possible that GSDMC downregulation is a secondary effect of S. TmWT infection or that its impact may only become evident at later stages of infection." (PMID 41370284, 2025). "While MMP and ECM proteins can be exploited by pathogens to promote invasion and infection (as reviewed in) it is not clear if pathogens can exploit GSDMC to modulate MMP-1 expression in the skin." (PMID 37266429, 2023). "Based on this observation we hypothesized that the absence of GSDMC could contribute to the tissue disruptive phenotype we see at 96 h of S. TmWT infection." (PMID 41370284, 2025).
bacterial infections (1 paper, 2025). "Yet, little is known about the role of GSDMC in bacterial infections." (PMID 41370284, 2025).
GSDMC also shares sentences with these, for which no sentence is quoted: small cell lung carcinoma (2 papers); asthma (1); bone disorder (1); celiac disease (1); COVID-19 (1); Crohn disease (1); depression (1); inflammatory bowel disease (1); leukemia (1); non-small cell lung carcinoma (1); ovarian serous cystadenocarcinoma (1); prostate adenocarcinoma (1); prostate carcinoma (1); stomach adenocarcinoma (1); uterine carcinosarcoma (1); uveal melanoma (1).